ANXA9 (annexin A9)
Description:
Plays a role in epidermal differentiation. Can bind acetylcholine.
Synonyms: ANX31
Tractability: Antibody: its Gene Ontology location is reachable by antibodies, with medium confidence. PROTAC: its protein half-life has been measured.
Gene: Protein-coding gene on chromosome 1 (150,981,321 to 150,996,077, forward strand). Ensembl gene ENSG00000143412.
Subcellular location: Lateral cell membrane
Subcellular location (Human Protein Atlas): Cytosol; Nuclear speckles
Gene Ontology:
Molecular function: acetylcholine receptor activity; phosphatidylserine binding; phospholipid binding; protein binding; calcium-dependent phospholipid binding; calcium ion binding
Biological process: cell-cell adhesion; cell adhesion; synaptic transmission, cholinergic
Cellular component: cell surface; cytosol; lateral plasma membrane; nucleus; plasma membrane; vesicle membrane; synapse
Genetic constraint (gnomAD): Loss-of-function variants: 47 observed, 54.95 expected, observed/expected ratio (o/e) 0.86, 90% interval 0.68 to 1.09. The upper end of that interval is the gene's LOEUF score, 1.09, which puts it in group 4 of 6, group 1 being the genes least tolerant of losing a copy. Missense variants: 361 observed, 445.24 expected, observed/expected ratio (o/e) 0.81, 90% interval 0.74 to 0.88. Synonymous variants: 154 observed, 178.38 expected, observed/expected ratio (o/e) 0.86, 90% interval 0.76 to 0.99.
Homologues: Orthologues: macaque ANXA9 (94% identical), chimpanzee ANXA9 (84% identical), dog ANXA9 (82% identical), pig ANXA9 (82% identical), guinea pig ANXA9 (81% identical), rat Anxa9 (78% identical), mouse Anxa9 (78% identical), rabbit ANXA9 (69% identical), zebrafish anxa14 (33% identical), Drosophila melanogaster AnxB11 (29% identical), Drosophila melanogaster AnxB9 (28% identical), zebrafish anxa13 (27% identical), and 1 more. Paralogues in human: ANXA2 (40% identical), ANXA11 (34% identical), ANXA5 (34% identical), ANXA3 (33% identical), ANXA4 (33% identical), ANXA8 (33% identical), ANXA8L1 (33% identical), ANXA1 (33% identical), ANXA6 (33% identical), ANXA7 (31% identical), ANXA10 (29% identical), ANXA13 (28% identical).
Diseases named in the same sentence as ANXA9 in open-access papers:
ANXA9 is named in the same sentence as 34 diseases in open-access papers, as found by Europe PMC text mining. Sharing a sentence is not in itself a finding about the gene and the disease. The quoted sentences say what the papers report.
colorectal cancer (13 papers, 2014 to 2025). A primary or metastatic malignant neoplasm that affects the colon or rectum. "The association of ANXA9 with pathogenic prognosis in colorectal cancer contrasts with a proposed tumor suppressor role for ANXA10 in gastric cancer." (PMID 30744186, 2019). "ANXA9 protein expression in colorectal cancer was higher than in normal mucosa, and associated with invasion and lymphatic metastasis and, consequently, a worse prognosis." (PMID 30744186, 2019). "A previous study has shown that ANXA9 expression is associated with bone metastasis in breast cancer, whereas its significance in colorectal cancer (CRC) is unknown." (PMID 25289111, 2014). "ANXA9 expression levels have been correlated with the depth of invasion and lymphatic metastasis of colorectal cancer." (PMID 36936694, 2023). "It has been reported that ANXA9 promotes metastasis of colorectal cancer and predicts poor prognosis." (PMID 37294149, 2023). "Patients with colorectal cancer with high ANXA9 expression had statistically relatively worse prognosis." (PMID 34484309, 2021). "ANXA9 shows generally restricted tissue expression but is known to exhibit altered expression in breast cancer, colorectal cancer and cutaneous melanoma." (PMID 30744186, 2019). "Notably, ANXA9 has been reported to be a new prognostic biomarker for gastric and colorectal cancers." (PMID 37294149, 2023). "Patients with colorectal cancer and positive ANXA9 expression were found to have a poorer prognosis, which indicates that ANXA9 could be an independent risk factor for survival." (PMID 36936694, 2023). "In colorectal cancer, patients with high ANXA9 gene expression also had lower overall survival." (PMID 30744186, 2019). "Annexin A9 (ANXA9), a member of the annexin protein family, has been reported to be involved in the invasion and metastasis of various cancer cells, such as colorectal cancer (CRC), breast cancer, and head and neck squamous cell carcinoma cells." (PMID 33680718, 2021). "Transcriptomic analysis via RNA sequencing revealed upregulation of genes implicated in colitis and colorectal cancer (CRC) progression, such as Anxa9, Atp2a1, and Hepacam2, in ERAP1+/− mice, regardless of sulfasalazine administration." (PMID 40977735, 2025). "Annexin A9 has not been as extensively studied, but it has been reported as a predictor of prognosis in colorectal cancer and epithelial cancer." (PMID 37833989, 2023). "Except ANXA9 and ANXA13, changes in the expression of individual ANXs were observed in a diversity of cancers, including gastric carcinoma, colorectal cancer, pancreatic cancer, breast cancer, glioma, kidney cancer, hepatocellular, carcinoma, melanoma, but not in cervical cancer." (PMID 27402115, 2016).
breast carcinoma (12 papers, 2014 to 2024). "In breast cancer, ANXA9 gene expression is associated with bone metastasis and a patient's prognosis." (PMID 33680718, 2021). "One study showed that ANXA9 gene expression is associated with bone metastasis in breast cancer." (PMID 30744186, 2019). "In breast cancer, ANXA9 has been reported as a gene that is associated with the relapse in bone." (PMID 25289111, 2014). "Likewise, ANXA9 expression has been associated with a higher incidence of bone metastasis in breast cancer and so included in a predictive gene panel, and related to breast cancer prognosis." (PMID 36247003, 2022). "We found highly expressed ANXA9 in metastatic breast cancer tissues, which is correlated with breast cancer progression." (PMID 38609357, 2024). "Abnormal expression of the Annexin family has been observed in different malignant tumors, including upregulated ANXA9 in breast cancer." (PMID 38609357, 2024). "In vitro, the functional experiments indicated ANXA9 influenced breast cancer proliferation, motility, invasion, and apoptosis; in vivo, downregulation of ANXA9 suppressed breast cancer xenograft tumor growth and lung metastasis." (PMID 38609357, 2024). "In summary, our study is the first to demonstrate miR-186-5p-ANXA9 signaling in suppressing human breast cancer." (PMID 37841425, 2023). "In order to further demonstrate miR-186-5p induction of cell apoptosis by inhibiting ANXA9 in breast cancer, we knocked down ANXA9 by si-ANXA9 in MDA-MB-231 cells to mimic the overexpression of miR-186-5p, followed by the cell apoptotic analysis." (PMID 37841425, 2023). "The clinical relevance of miR-186-5p-ANXA9 was further confirmed by analysis of patients with breast cancer." (PMID 37841425, 2023). "Since ANXA9 was identified as a target gene of miR-186-5p, we analyzed the expression pattern of ANXA9 in breast cancer patients." (PMID 37841425, 2023). "ANXA9 showed obvious upregulation in both subtypes of breast cancer, which was further validated by additional breast tumor samples from the Human Protein Atlas database." (PMID 37841425, 2023). "Our findings demonstrate significant involvement of ANXA9 in promoting breast cancer progression, thereby suggesting that therapeutic intervention via targeting ANXA9 may be effective in treating metastatic breast cancer." (PMID 38609357, 2024). "We demonstrated miR-186-5p as a tumor suppressor in breast cancer by targeting ANXA9." (PMID 37841425, 2023). "Moreover, our analysis of the ANXA9 mRNA levels by QRT-PCR further demonstrated suppression of ANXA9 in expression by miR-186-5p in breast cancer cells." (PMID 37841425, 2023). "Although exosome-derived ANXA9 was reported to function as an oncogene in breast cancer, the expression pattern and regulatory function of endogenous ANXA9 in breast cancer cells remain unclear." (PMID 37841425, 2023). "The current study demonstrated the miR-186-5p-ANXA9 signaling in suppressing human breast cancer." (PMID 37841425, 2023). "Notably, an opposite correlation was observed in BC patients with less aggressive grades I and II, suggesting that ANXA9 regulation of breast cancer may be related with the tumor aggressiveness and cancer progression." (PMID 37841425, 2023). "The Anxa9 gene, part of the calcium-dependent phospholipid-binding annexin family, may play a role in suppression of apoptosis and is currently under investigation as a therapeutic target for the treatment of breast cancer." (PMID 25165739, 2014). "As expected, a positive correlation between the expression levels of ANXA9 and BCL2 was observed in breast cancer patients (n = 1104), as well as a negative correlation between miR-186-5p and BCL2 (n = 1085)." (PMID 37841425, 2023).
breast carcinoma (continued). "Additional gene expression analysis of clinical tumor samples indicated a negative correlation between miR-186-5p and ANXA9 in human breast cancer." (PMID 37841425, 2023). "Moreover, we detected the mRNA levels of ANXA9 and miR-186-5p in 21 tumor tissues and matching adjacent normal tissues from human breast cancer patients." (PMID 37841425, 2023).
gastric cancer (7 papers, 2016 to 2024). A primary or metastatic malignant neoplasm involving the stomach. "In gastric cancer, ANXA9 upregulation has also been associated to poor prognosis in gastric cancer patients." (PMID 36247003, 2022). "ANXA9 has been shown to be highly expressed in gastric cancer tissues and proposed as a new prognostic biomarker associated with immune infiltration in gastric cancer." (PMID 37294149, 2023). "Upregulation of ANXA9 was reported in gastric cancer, accelerating the malignant progression through regulating the TGF-β pathway." (PMID 37841425, 2023). "Furthermore, the overexpression of ANXA9 has been found to increase the migration of gastric cancer and form larger and more cell clones, which decrease in the G1 phase and increase in the S and G2 phases." (PMID 36936694, 2023). "ANXA9 was reported to regulate cell proliferation and migration in gastric cancer." (PMID 37841425, 2023). "In addition, ANXA9 was able to promote cell migration and growth in gastric cancer cell lines via TGF-β signaling, which reinforces its oncogenic role in these tumors." (PMID 36247003, 2022). "Several studies revealed that high expression of ANXA9 could promote cancer cellular proliferation and migration via activating the transforming growth factor-β (TGF-β) pathway in gastric cancer." (PMID 38609357, 2024).
ovarian carcinoma (7 papers, 2019 to 2024). A malignant neoplasm originating from the surface ovarian epithelium. "ANXA9 expression was also associated with a poor prognosis in ovarian cancer and resistance to cisplatin in vitro and in vivo, posing ANXA9 as an interesting candidate for targeted therapies to overcome cisplatin-resistant cancers." (PMID 36247003, 2022). "Downregulation of SULT2B1 in ovarian cancer cell lines reduces cell proliferation, migration, and invasion by binding to annexin A9 (ANXA9) and regulates its expression." (PMID 39280099, 2024). "Previously, ANXA9 overexpression was confirmed to promote cisplatin resistance in ovarian carcinoma cells." (PMID 37294149, 2023). "miR-105-1 can affect Annexin A9 (ANXA9) expression, enhancing chemo-resistance and attenuating the cell apoptosis induced by cisplatin in cisplatin-sensitive ovarian cancer cells." (PMID 39596302, 2024). "Therefore, genetic variations in ANXA9 and ANXA13 genes may be correlated with ovarian cancer tumorigenesis and progression." (PMID 31474227, 2019).
melanoma (4 papers, 2016 to 2024). A malignant, usually aggressive tumor composed of atypical, neoplastic melanocytes. "In addition, a previous melanoma GWAS and a recent transcriptome-wide association study of cSCC identified ANXA9 as a susceptibility locus." (PMID 35449187, 2022). "Finally, the locus at 1q21.3 contains a large LD block covering multiple genes, among which ANXA9 is associated with melanoma." (PMID 30946739, 2019). "Genes in cluster 8 (GSTO2, LRRC34), 9 (CLPTM1L) and 10 (CTSS, SETDB1, ANXA9, GOLPH3L, HORMAD1, PPIL3, CASP9, ALS2CR12) underlie the association between melanoma and cancers." (PMID 38308491, 2024).
head and neck squamous cell carcinoma (3 papers, 2020 to 2022). A squamous cell carcinoma that arises from any of the following anatomic sites: lip and oral cavity, nasal cavity, paranasal sinuses, pharynx, larynx, and salivary glands. "ANXA9 showed high expression in head and neck squamous cell carcinomas and was associated with the tumour differentiation grade." (PMID 39290334, 2022). "In head and neck squamous cell carcinomas, the level of ANXA9 is frequently altered and associated with the tumor's differentiation grade, suggesting that ANXA9 is associated with the pathogenesis of these cancers." (PMID 33680718, 2021). "ANXA9 and ANXA10 expression is altered in head and neck squamous cell carcinomas (HNSCC)." (PMID 32824294, 2020).
breast tumor (2 papers, 2023 to 2024). "The expression of miR-186-5p showed significant downregulation, whereas ANXA9 showed upregulation in breast tumor tissues, compared with normal controls." (PMID 37841425, 2023).
bladder cancer (1 paper, 2021). "However, in our study, patients with higher ANXA9 expression were more likely to show luminal-subtype bladder cancer and have a better prognosis." (PMID 34484309, 2021). "ANXA1, ANXA2, ANXA3, ANXA5, ANXA6, ANXA7, and ANXA9 had prognostic value in bladder cancer." (PMID 34484309, 2021). "The expression of ANXA1, ANXA2, ANXA3, ANXA5, ANXA6, ANXA8, and ANXA13 was closely related to basal-subtype bladder cancer, while the expression of ANXA4, ANXA9, ANXA10, and ANXA11 was closely related to luminal-subtype BC." (PMID 34484309, 2021). "We also analyzed the possible role of ANXA-L (ANXA4, ANXA9, ANXA10, and ANXA11) in the regulation of luminal bladder cancer." (PMID 34484309, 2021). "Similarly, the expression of ANXA9–11 and ANXA13 in high-grade bladder cancer was lower than that in low-grade bladder cancer." (PMID 34484309, 2021). "We used TCGA data to find that in addition to ANXA1 and ANXA2, other ANXA family proteins (ANXA3, ANXA5, ANXA6, and ANXA9, which have not been studied) are also closely related to the prognosis of bladder cancer." (PMID 34484309, 2021).
bladder tumors (1 paper, 2021). "ANXA2, ANXA3, ANXA4, ANXA8, and ANXA9 were significantly increased in bladder tumor tissues, while ANXA6, ANXA7, and ANXA11 were significantly decreased." (PMID 34484309, 2021).
colitis (1 paper, 2025). Inflammation of the colon. "Anxa9, a novel marker associated with poor prognosis, was significantly upregulated in ERAP1+/− colitis mice compared to ERAP1+/− controls (p < 0.05), with a further significant increase observed following sulfasalazine treatment (p < 0.05)." (PMID 40977735, 2025). "Notably, mRNA expression levels of Anxa9 (p < 0.05), Atp2a1 (p < 0.001), and Hepacam2 (p < 0.01) were all significantly upregulated in ERAP1+/− colitis mice relative to WT colitis mice after sulfasalazine treatment, indicating its potential role in colitis pathogenesis and therapeutic response." (PMID 40977735, 2025).
lupus (1 paper, 2021). "In addition, we found that the expression of CD27, Anxa9, CCR9, and IL17Rβ were decreased in M-MDSCs from pristane-induce lupus mice, and INK128 could increase the expression of these genes." (PMID 34282122, 2021).
non-small cell lung carcinoma (1 paper, 2022). A group of at least three distinct histological types of lung cancer, including non-small cell squamous cell carcinoma, adenocarcinoma, and large cell carcinoma. "ANXA9 which is related to metastasis, and the transcription factor activating enhancer-binding protein 2C (TFAP2C) that has been reported to decrease migration and invasion in pancreatic ductal adenocarcinoma and non-small cell lung cancer cells." (PMID 35872983, 2022).
oropharyngeal tumors (1 paper, 2019). "We also observed differences in ANXA9 expression between the different HNSCC subsites, with ANXA9 expression being significantly higher in oropharyngeal tumors (p < 0.001)." (PMID 30744186, 2019). "Similar to ANXA9, ANXA10 expression was significantly higher in oropharyngeal tumors (p = 0.019)." (PMID 30744186, 2019).
ovarian serous tumor (1 paper, 2019). A benign, borderline, or malignant epithelial tumor of the ovary characterized by the presence of neoplastic epithelial cells that, in well differentiated tumors, resemble the epithelial cells of the fallopian tube and, in poorly differentiated tumors, show anaplastic features. "Upregulation of ANXA2, ANXA4, ANXA8, and ANXA9 mRNAs displayed significant correlations with poor OS in patients with ovarian serous tumors." (PMID 31474227, 2019). "ANXA7 mRNA downregulation was significantly correlated with poor PFS in patients with ovarian serous tumors, and ANXA9 mRNA upregulation was significantly correlated with poor OS and PFS in patients with ovarian serous tumors." (PMID 31474227, 2019). "Taken together, these data indicated that the upregulation of ANXA8 and ANXA9 mRNAs was significantly correlated with poor OS and PFS in patients with ovarian serous tumors." (PMID 31474227, 2019).